APOA1 (apolipoprotein A1)
Diseases named in the same sentence as APOA1 in open-access papers (continued):
Sharing a sentence is not in itself a finding about the gene and the disease.
dyslipidemia (continued). "Dyslipidemia is the principal cause of the excess burden of CAD in South Asians, which is characterized by increased levels of apolipoprotein (apo) B, TG, Lipoprotein Lp(a) and LDL-C, and low levels HDL-C and apoA1." (PMID 30542628, 2018). "Comparison of genotype distributions and allele frequencies of polymorphisms in the APOA1/C3/A4/A5 gene cluster between subjects with and without metabolic syndrome." (PMID 26824674, 2016). "The change in apoA1 levels by age in women seems to indicate more dyslipidemia in younger women." (PMID 21159217, 2011). "The objective of the current study is to assess the prevalence of metabolic syndrome (MS), its association with high density Lipoprotein (HDL) function, Apo lipoprotein A-I (APOA1) gene polymorphisms, and sub-clinical CAD using common carotid intima-media thickness (CCA-IMT) as a surrogate marker." (PMID 21410987, 2011). "Additionally, resveratrol reduces lipoprotein(a) [Lp(a)] levels, hepatic 3-hydroxy-3-methylglutaryl-coenzyme A (HMG-CoA) reductase activity, and cholesterol ester transport protein concentrations while increasing apolipoprotein A1 (ApoA1), effectively ameliorating dyslipidemia." (PMID 40692591, 2025). "This disruption may lead to dyslipidemia, which is characterized by elevated triglycerides and low cholesterol levels, an elevated apolipoprotein B-to-apolipoprotein A1 ratio and an increase in low-density lipoprotein cholesterol, and is associated with increased blood pressure." (PMID 40391041, 2025). "The phenotype of obesity and metabolic syndrome observed in our mouse model closely mirrors human genomic studies that demonstrate associations of HDAC5 with whole body fat mass, height, HDL cholesterol levels, apolipoprotein A1 levels, and diastolic blood pressure." (PMID 39304061, 2024). "Notably, among the apoA1-proriasis and TC-psoriasis shared SNPs, none of them were found to be associated with dyslipidemia or obesity." (PMID 38550599, 2024). "SNPs in the apolipoprotein A1 and C3 (APOA1 and APOC3) genes and cluster of differentiation 36 (CD36) gene led to increased risk of metabolic syndrome in subjects with Western dietary pattern and dyslipidemia in individuals who consumed high amounts of fat, respectively." (PMID 37610590, 2023). "In certain conditions such as metabolic syndrome where the underlying mechanism of loss of function is the loss of total numbers of HDL particles, the measurement of HDL-C, total HDL particle count, and total ApoA1 in plasma may be adequate." (PMID 37894984, 2023). "Therefore, it may be hypothesized that the variants of APOA1 and APOC3 might confer to hypertriglyceridemia, thereby leading to characteristic feature of atherogenic dyslipidemia among this south Indian population." (PMID 28610615, 2017). "The rs2483058C-rs2580520G haplotype was associated with an increased risk of dyslipidemia, and showed consistent association with serum total cholesterol (TC), high-density lipoprotein cholesterol (HDL-C), apolipoprotein (Apo) A1 levels, and the ApoA1/ApoB ratio." (PMID 28912560, 2017). "Particularly, the variants rs632153, rs633389, rs2187126 and rs1263163 might be risk conferring to dyslipidemia by elevating LDLC and TC levels, while the variants of APOC3 and APOA1 genes might be the genetic determinants of elevated triglycerides in the present population." (PMID 28610615, 2017). "HP infection may cause dyslipidemia, as it increases total cholesterol, LDL, lipoprotein a, apolopoprotein apo-B, and triglyceride concentration and decreases HDL and the apolipoprotein apoA-1 concentration." (PMID 28224026, 2016). "However, whether apoB/apoA1 ratio is a better indicator of metabolic syndrome than other biomarkers and what is the optimal cut-off value of apoB/apoA1 ratio as an indicator of metabolic syndrome in Chinese population remain unknown." (PMID 24886173, 2014).
dyslipidemia (continued). "Eradication therapy:Can partially reverse dyslipidemia.Is accompanied by the downregulation of key lipid regulatory genes (e.g., FABP1, MTP).Consistently increases HDL-C and apolipoprotein A1 (ApoA1) levels." (PMID 41158522, 2025). "On the contrary, apoA1 functions as a major structural component of HDL-cholesterol, as one component of the metabolic syndrome (dyslipidemia, hypertension, and abdominal obesity)." (PMID 38427666, 2024). "SLE patients showed a pattern of dyslipidemia and dyslipoproteinemia, characterized with the increase of serum TG, TC, LDL, and ApoB, while the decrease of serum HDL and ApoA1." (PMID 36790644, 2023). "Conditions where the pathology is a loss of HDL particles, such as that which has been observed in obesity and metabolic syndrome, can be measured by simple metrics such as HDL-C concentration, total amount of ApoA1, and total particle number." (PMID 37894984, 2023). "Our results indicate that elevated biomarkers of metabolic syndrome, higher plasma TG/HDL-C ratios, and plasma ApoA1 levels had a faster cognitive and functional rate of decline in both MCI and AD dementia participants." (PMID 36927447, 2023). "Dyslipidemia is another kind of metabolic disorders occurred in T2DM with increased LDL-c and decreased HDL-c and its major apolipoproteins (APOA1)." (PMID 36419622, 2022). "T2DM are often accompanied with dyslipidemia like increased low-density lipoprotein cholesterol (LDL-c) and decreased high-density lipoprotein cholesterol (HDL-c) and apolipoprotein A1 (APOA1)." (PMID 36419622, 2022). "The highest prevalence of OB, high TG, high TC, high LDL, high APOB, and dyslipidemia were found in CM-Mexico City and NM-Urban, while the highest prevalence of low HDL and low ApoA1 were found in CM-Puebla and NM-Yaquis, respectively." (PMID 34886385, 2021). "Dyslipidemia occurs when there is an increased level of apolipoprotein (apo) B, TG, Lipoprotein Lp(a) and LDL-C, and low levels HDL-C and apoA1." (PMID 32021736, 2019). "In brief, patients with high GS had higher percentage of smoking, hypertension, dyslipidemia and DM, higher level of TC, LDL-C, Lp(a), apoB, fasting blood glucose, hemoglobin A1C (HbA1C), and lower levels of HDL-C, apoA1 and LVEF." (PMID 25426943, 2014). "Dyslipidemia was present with elevated triglycerides (3.7–8.5 mmol/l), an abnormal cholesterol profile (HDL 0.4–0.7 mmol/l, LDL 2.1–2.3 mmol/l) and reduced apolipoprotein A1 (0.53–0.81 g/l)." (PMID 20300641, 2010). "In conclusion, this study demonstrates that insulin resistance and dyslipidemia are major determinants of metabolic disturbances among obese individuals, independent of glycemic status or APOA1 rs5069 genotype." (PMID 41422312, 2025). "The ApoB:ApoA1 ratio is an effective biomarker for predicting metabolic syndrome and coronary artery disease independent of LDL and HDL cholesterol markers." (PMID 38609170, 2024). "In Brazil, 83.3% of the patients with JIA demonstrated dyslipidemia based on the TC, HDLc, LDLc, TG, non-HDLc, apolipoprotein A1 (ApoA1), and apolipoprotein B (ApoB) concentrations." (PMID 36832332, 2023). "Consumption of 364 mg of anthocyanin from fresh blueberries has been proven to statistically increase FMD, HDL-C and Apolipoprotein A1 values in patients with metabolic syndrome, but not SBP and DBP." (PMID 37242181, 2023). "Many genes such as APOB, LPL, APOA1, LEP, CD36, IL-6, and APOE may play an important role in dyslipidemia." (PMID 36061816, 2022). "Elevated plasma BCAA were also associated with an unfavorable fasting blood lipid profile in our subjects, including higher TG, LDL-C and ApoB/ApoA1 ratio and lower HDL-C, consistent with the BCAA-dyslipidemia links established in Asian and Caucasian populations." (PMID 33996878, 2021).
dyslipidemia (continued). "In addition, CCQS-specific and QSBS-specific genes were also enriched in metabolic Syndrome and cerebrovascular disease, respectively, in which Syndrome-specific DPs involved in the diseases were PON1 and ADIPOQ for CCQS, APOE and APOA1 for QSBS." (PMID 34702323, 2021). "However, to the best of our knowledge, there have been few studies conducted in northeast Chinese populations that explore the relationship between the APOA1/C3/A4/A5-ZPR1-BUD13 gene cluster and dyslipidemia." (PMID 30631647, 2019). "Our results show that the pro-atherogenic lipid profile characteristic of women with severe obesity and the metabolic syndrome turns into a healthier one after bariatric surgery, with a significant increase in HDL and ApoA1, and a decrease in LDL, oxLDL and ApoB." (PMID 29925393, 2018). "In the LIPGENE-SU.VI.MAX study, the ApoB rs512535 and ApoA1 rs670 major G allele homozygotes had increased MetS risk (OR 1.65 and OR 1.42, respectively), which may be explained by their increased abdominal obesity and impaired insulin sensitivity but not dyslipidemia." (PMID 23306188, 2013). "In our study, TG/HDL and LDL/HDL, which are considered as a better predictor of metabolic syndrome and insulin resistance than apolipoprotein B/apolipoprotein A1, were negatively correlated with QUICKI, indicating the close relationship between dyslipidemia and IR." (PMID 24391852, 2013). "Compared to healthy controls, GBS patients displayed a distinct dyslipidemia characterized by elevated triglycerides (TG), very low-density lipoprotein (VLDL), and residual cholesterol (RC), but decreased high-density lipoprotein (HDL) and apolipoprotein A1 (APOA1)." (PMID 42051772, 2026). "Dyslipidemia is characterized by aberrant levels of circulating lipids and apolipoproteins, including total cholesterol (TC), triglycerides (TG), high-density lipoprotein cholesterol (HDL-C), low-density lipoprotein cholesterol (LDL-C), apolipoprotein A1 (ApoA1), and apolipoprotein B (ApoB)." (PMID 41430991, 2025). "Dyslipidemia is a prominent metabolic disease characterized by abnormal changes in lipids including high-density lipoprotein (HDL) cholesterol, low-density lipoprotein (LDL) cholesterol, total cholesterol (TC), triglyceride (TG), apolipoprotein A-I (APOA1), and apolipoprotein B (APOB)." (PMID 39857597, 2024). "In female non-metabolic syndromes, Bifidobacterium lost its probiotic character; instead, showing pathogenicity, which has strong positive correlations with fasting blood glucose and low-density lipoprotein but negative correlations with Apolipoprotein A1." (PMID 37744899, 2023). "In general, dyslipidemia is characterized by high circulating concentrations of low-density lipoprotein-cholesterol (LDL-C), triglycerides (TGs), and apolipoprotein B (ApoB); and low circulating concentrations of high-density lipoprotein-cholesterol (HDL-C) and apolipoprotein A1 (ApoA1)." (PMID 36545018, 2022). "However, more basic researches are needed to confirm whether IS has a direct effect on any step of RCT, ApoA-1 mediated cholesterol efflux, HDL biogenesis and maturation, the results of which might bring new target on dyslipidemia therapy in CKD patients." (PMID 33191829, 2020). "The absence of Apoa1 could result in at least a 70% reduction in plasma HDL levels, which was a risk factor of atherogenic dyslipidemia and obesity." (PMID 27877172, 2016). "It remains unclear whether apoB/apoA1 ratio is a better indicator for identifying metabolic syndrome in the Chinese population, and there are no optimal cut-off values of apoB/apoA1 ratio for Chinese men and women yet." (PMID 24886173, 2014). "Although apolipoprotein A1 and B measurements were unavailable in three cohorts, the high correlations with high-density and low-density lipoprotein concentrations (r>0.70 in ARIC data) suggested that all five cohorts provided similar atherogenic dyslipidemia phenotypes." (PMID 22022282, 2011).
Hypertension (170 papers, 2008 to 2026). The presence of chronic increased pressure in the systemic arterial system. "They found that hCRP correlated with disease severity (PASI score) and the ApoB/ApoA1 ratio, while metabolic parameters were linked to blood pressure, hypertension, weight, and BMI." (PMID 40137160, 2025). "For the HDL group, hypertension reduced the risk of the infection by 9% (OR = 0.91, p < 0.001), while it increased it in the apoA1 group (OR = 1.25, p = 0.04)." (PMID 37372137, 2023). "ApoA1 has anti-atherogenic effects, and some APOA1 polymorphisms are associated with MetS: the G-75A with hypertension and C+83T with obesity and with higher levels of glycated hemoglobin." (PMID 37510094, 2023). "ApoA1 rs670 genetic variations involved in the synthesis, transport, and processing of HDLs, hypertension, and inflammation are linked to arterial stiffness." (PMID 35873099, 2022). "Both in pre-symptomatic individuals and controls, current smoking, hypertension, and an elevated ApoB:ApoA1 ratio were significantly associated with a future CVE, whereas an elevated BMI was significant only in the controls." (PMID 36362763, 2022). "APOA1 polymorphisms (−75 G and +83 C-alleles) were associated with hypertension." (PMID 36551995, 2022). "For apolipoproteins, apoA1 and apoE polymorphism were closely associated with hypertension." (PMID 36551995, 2022). "The polymorphisms in apoA1 are also closely associated with hypertension." (PMID 36551995, 2022). "But only ApoB/ApoA1 was positively correlated with inflammatory marker hCRP and the concomitant of arthritis, and they were all associated with diastolic blood pressure or the concomitant of hypertension, weight, or BMI in a stepwise regression analysis." (PMID 34996506, 2022). "Moreover, heterozygosity in the apoA1 gene was associated with higher odds of developing essential hypertension." (PMID 36551995, 2022). "ApoA1/ApoB was associated with renal function decline and hypertension (P<0.05 for all)." (PMID 33112407, 2020). "Baseline urinary Hcy‐thiolactone/creatinine was significantly associated with plasma tHcy, ApoA1, glomerular filtration rate, potassium and pyridoxal 5′‐phosphate (positively) and with age, hypertension, smoking, urinary creatinine, plasma bilirubin and kynurenine (negatively)." (PMID 30193001, 2019). "It has been found that the APOA1 polymorphisms (−75 G/A and +83 C/T) could be as risk factors for hypertension and obesity in a Brazilian elderly cohort." (PMID 26537097, 2015). "A Brazilian elderly cohort showed that APOA1 polymorphisms (-75 G/A and +83 C/T) could be as risk factors for hypertension and obesity." (PMID 26173491, 2015). "A cohort study found that the APOA1 -75 G allele showed significant association with hypertension." (PMID 24209603, 2013). "Only arterial stiffness in men was associated with ApoA1 (OR, 3.96; 95% CI [1.29–12.30], P < 0.05) in logistics regression models adjusted for age, gender, body mass index, education attainment, physical activity, smoking, history of hypertension and high-density lipoprotein." (PMID 32874784, 2020). "Their findings demonstrated a significant increase in the ApoB100/ApoA1 ratio in both stages of hypertension (stage I and stage II) compared to the control group." (PMID 38393015, 2024). "These indicators-Hypertension, CSVD Burden, ApoA1, and Age-demonstrated the strongest associations with cognitive impairment, underscoring their importance in the predictive model." (PMID 38952470, 2024). "After adjustment for age, BMI, diabetic duration, menopausal duration, hypertension, sedentary behavior, smoking, and drinking (model 1), APOA1 was independently correlated with osteoporosis, and the ORs (95%CI) was 0.889 (0.832–0.950)." (PMID 37396919, 2023). "A large cohort indicated the level of apoA1 was lower in women with hypertension as compared to healthy women after eight years." (PMID 36551995, 2022).
Hypertension (continued). "Elevated ApoB:ApoA1 ratio in combination with hypertension yielded a higher OR compared with the combination of hypertension with current smoking in the cases, while in controls these risk factor combinations acted to the opposite effect." (PMID 36362763, 2022). "None of the associations were changed when the main model was further adjusted for the potential mediators ApoB/ApoA-1 ratio, hypertension, and the use of lipid-lowering medications." (PMID 33425973, 2020). "Our results indicated that female patients with T2DM with older age, lower education level, hypertension history, higher HbA1c and ApoA1 levels, and lower plasma sLRP1 levels were highly likely to develop MCI (p < 0.05)." (PMID 33013281, 2020). "The lowest quartile of ApoB/ApoA1 was predominant for patients with first degree of hypertension (p < 0.05)." (PMID 32717783, 2020). "Multivariate logistic regression analysis here demonstrated a significant inverse relation between serum APOA1-UP level and the presence of ischemic stroke (p < 0.0001), adjusting for age, DM, hypertension, and previous IHD." (PMID 27043525, 2016). "There were significant differences between CAD and control groups in important risk factors including age, BMI, smoking, hypertension, DM, atrial fibrillation (AF), stroke, TG, HDL, Lp(a), BUN, uric acid, ApoA1, and ApoB." (PMID 24533640, 2014). "Several studies have linked apolipoproteins (APOA1, APOB and APOL1) with CKD and hypertension." (PMID 38402394, 2024). "However, in controls, hypertension, current smoking and elevated ApoB:ApoA1 ratio were significant in multivariable models, whilst increased BMI did not remain significant." (PMID 36362763, 2022). "Among SARS-CoV-2-positive cases and negative controls, a 10 mg/dl increase in serum HDL-cholesterol or apolipoprotein A1 levels was associated with ∼10% reduced risk of SARS-CoV-2 infection, after adjustment for age, sex, obesity, hypertension, type 2 diabetes, and coronary artery disease." (PMID 33667465, 2021). "In model 2, after adjusting for age, gender, BMI, education attainment, physical activity, smoking and history of hypertension, the relationship between ApoA1 and baPWV in male patients was statically significant (coefficient, 139.84; 95% CI [83.97–195.68], P < 0.001)." (PMID 32874784, 2020). "We anticipated that some of the genetic risk SNP for CAD would act through established CAD risk factors, including BMI, waist/hip ratio, LDL-C, HDL-C, total cholesterol, triglycerides, ApoA1, ApoB, ApoB/A1 ratio, blood pressure, heart rate, hypertension and type 2 diabetes." (PMID 24475106, 2014). "The INTERHEART study of potentially modifiable risk factors associated with myocardial infarction reported population attributable risks of 35.7%, 49.2%, and 17.9% for smoking, apolipoprotein B to apolipoprotein A1 ratio, and history of hypertension, respectively." (PMID 25003122, 2014). "The current research indicated, for the first time, that the ApoB/ApoA1 ratio and concentrations of serum GDF-15 were predictive indicators of CAD in Chinese patients with T2DM, independent of potential risk factors such as hyperglycemia, diabetic duration, hypertension and age." (PMID 35842724, 2022). "The clinical variables with the most importance to PD-MCI were years of education, hypertension, MDS-UPDRS Part III motor score and the blood-based variables were triglyceride and ApoA1." (PMID 39403068, 2024). "Significant variations were observed in waist circumference, BMI, ALP, GLU, TG, LDL, ApoA1, ApoB, LDH and vegetables consumption among female hypertension participants." (PMID 39512695, 2024). "In this study, a nomogram was developed to predict the probability of cognitive impairment in patients with CSVD, based on four identified predictive factors: Hypertension, CSVD Burden, ApoA1 levels, and Age." (PMID 38952470, 2024).